CD9 (CD9 molecule)
Diseases named in the same sentence as CD9 in open-access papers (continued):
Sharing a sentence is not in itself a finding about the gene and the disease.
tumor (continued). "Tumor sections with no CD9 positive clusters were classified as negative." (PMID 35563166, 2022). "Other studies have shown that CD63+/CD9+/Flotillin-1+ EVs from NPC (CNE2, CNE1, 5-8F, 6-18B) cells were enriched with a key glycolysis-regulatory enzyme, 6-Phosphofructo 2-kinase/fructose 2, 6-bisphosphatase 3, which promotes angiogenesis amongst other tumor permissive activities." (PMID 33158181, 2020). "Thus, it is not surprising that CD9 is one of the most useful markers for a range of cancers, with exosomes themselves being reported as a tumor biomarker." (PMID 30356731, 2018). "The requirement of CD9 for orthotopic tumor growth suggests that membrane extension-driven cell communication and/or reduced cell adhesiveness to stromal components are responsible for the absence of local tumor growth." (PMID 25762645, 2015). "Although the exact nature of the CD26 and CD9 association was not elucidated in the report, our current data clearly demonstrate that CD26+CD9+ cells exhibit higher invasive activity than CD26−CD9+ cells, suggesting that CD26 may potentiate tumor cell invasiveness." (PMID 24466195, 2014). "Other studies have considered that CD9 may downregulate the expression of Wiskott-Aldrich syndrome protein 2 (WAVE2) and that the decreasing WAVE2 then affects the actin cytoskeleton and suppresses tumor cell motility." (PMID 24520284, 2014). "Surprisingly, several CD9/CD81 functions, including promoting α3β1's association with PKCα and promoting α3β1-dependent tumor cell migration on LM-332, may not require CD151-dependent complex formation with α3β1 in this system." (PMID 23613949, 2013). "Whether CD9 expression has the same favorable prognostic value in RCC as it does in other tumor types has not been established." (PMID 19922654, 2009). "Thus, in this subgroup (membranous and cytoplasmic staining), the mean tumour CD9 values in patients with and without any oncological event were 37 and 65%, respectively (P=0.08)." (PMID 14735195, 2004). "In addition, both CM presented a remarkable quantity of different proteins that have been associated with antioxidant and/or anti-inflammatory effects and may thus mediate the viability of non-tumor cells, such as AIFM1, ANXA5, CD9, CDH13, GDF15, GSR and TIMP2." (PMID 34884877, 2021). "In the context of cancer, it has been demonstrated that blood injections of antibodies against CD63 and/or CD9, two tetraspanins expressed at the surface of all EVs, could significantly reduce the development of metastasis without any effects on tumor growth in mice." (PMID 33670146, 2021). "Our results demonstrated that laminin, not fibronectin, is the primary target of tumor-derived sEVs containing CD63, CD81, or CD9." (PMID 40304687, 2025). "TEX harvested from tumor cell supernatants by SEC had vesicular morphology, were sized at 50–200 nm (median = 105 nm), and carried CD9, TSG101, and ALIX but were negative for calnexin." (PMID 40121518, 2025). "In that report, anti-CD9 and CD63 antibodies did not affect vascular generation in the primary tumor, and, moreover, these antibodies did not affect tumor cell proliferation and invasion." (PMID 36289745, 2022). "Therefore, we assessed whether correlation with worse PS (and thus greater tumour load) could be found with different levels of those exosomal proteins resulted to stratify patients in different clusters after hierarchical cluster analysis: EpCAM, CXCR4, CD81 and CD9." (PMID 31048929, 2019). "Western blotting revealed that the isolated exosomes were positive for CD9 and negative for cytochrome-c and the SS18-SSX fusion gene was separately detected in the tumour-derived exosomes." (PMID 29116117, 2017). "Late or absent tumor progression was accompanied by a persistent reduction in both CD9+/SVN+ and CD9+/GFAP+/SVN+ exosomes in 2 of 3 patients as well." (PMID 29383115, 2017).
tumor (continued). "Several genes thought to play a role in the processes of invasion, tumour progression and metastasis (MME, STAT3, DCBLD2, S100A10, CD9, S100A8) were highly downregulated in the NE vs the non-NE tumour group." (PMID 18827820, 2008). "Tumor location does not influence the preferential release of these sEV subpopulations; the percentages of CD63/81+ and CD9/63/81+ sEVs demonstrated a significant increase post-brachytherapy in both anterior and posterior tumors (12 anterior vs. 7 posterior pairs)." (PMID 38892225, 2024). "A study comparing stromal stem cells (menstrual blood-derived) from females with EMs and non-EMs found higher CD9, CD10, and CD29 expression levels in women with EMs, suggesting that EMs share the same properties as tumor cells, namely the invasive growth of diseased tissue." (PMID 36212136, 2022). "Moreover, SP-IRIS demonstrated the presence of EVs that were double-positive for CD9, CD63, and CD81 and negative for the platelet marker CD41, which indicated low contamination of blood-derived EVs in the tumor EV isolates." (PMID 36531960, 2022). "The recognized exosomal markers CD63, CD9, and CD81, are not tumor-specific." (PMID 34707986, 2021). "On the other hand, the expression of CD166, CD133, CD44, A2B5, CD56, NGFR and DCX seemed to be higher in UA cells, but also not statistically significant, while the expression of CD9, Nestin, GFAP, CD24, PDGFRb, PDGFRa, MAP2, TUBIII, S100 were consistently high in both UA and tumor core samples and." (PMID 27605047, 2016). "Thus, its interesting to note that several genes thought to play a role in the processes of invasion, tumour progression and metastasis (MME, STAT3, DCBLD2, S100A10, CD9, S100A8) were highly downregulated in the NE vs the non-NE tumour group." (PMID 18827820, 2008). "In addition, less intense punctuated fluorescence signal was observed upon the uptake of CD9-RFP CS carrying EVs with respect to their non-cleavable counterpart, confirming not only the internalization, but also the tumor specific cell-processing of the EV cargo." (PMID 36579638, 2023).
cancer (268 papers, 1999 to 2026). A tumor composed of atypical neoplastic, often pleomorphic cells that invade other tissues. "CD9 expression levels are associated with the invasiveness and prognosis of tumors in cancer research." (PMID 40196737, 2025). "CD9, a cell surface protein belonging to the tetraspanin superfamily, has been implicated in cancer progression, with its impact on disease outcomes contingent upon the context." (PMID 38001171, 2024). "Because CD9 is a pleiotropic protein that adversely affects the prognosis in patients with cancer, including intercellular communication in the immune system, it is possible that using the native form of CD9 as an EV tag can cause unexpected impacts in vivo." (PMID 39418272, 2024). "CD9 was also upregulated 4.1-fold in mass-type cancer, which is associated with the chemoresistance to doxorubicin and 5-fluorouracil." (PMID 37391754, 2023). "Remarkably, only the CD9 fused RFP was correctly managed by 5637 cancer cells, whereas transfection with CD81 variant resulted in a series of possible degradation products." (PMID 36579638, 2023). "CD9 expression is deregulated in a number of pathologies, including cancer, but the precise mechanism underlying these changes and the associated consequences are not fully understood." (PMID 37007105, 2023). "CD9 on lung adenocarcinoma cells is also necessary for the pro-invasion effect of the secreted TIMP-1 from cancer-associated fibroblasts, probably depending on the direct interaction between these two proteins." (PMID 36941633, 2023). "Cathepsin B specific smart prodrug system appeared to be a promising strategy in releasing a protein drug specifically to cancer cells when associated to the CD9 tetraspanin." (PMID 36579638, 2023). "MMP9+/MMP2+/EMMPRIN+ subpopulation of CD9-positive blood plasma exosomes reduced the cancer risk in CPPs." (PMID 33773551, 2021). "Eleven studies consisting of 1141 cancer patients reported an association between CD9 expression and OS." (PMID 34493282, 2021). "Eleven studies consisting of 2859 cancer patients reported an association between CD9 expression and DFS, progression-free survival, and recurrence-free survival." (PMID 34493282, 2021). "CD9 is implicated in cancer progression and metastasis by its role in suppressing cancer cell proliferation and survival." (PMID 34493282, 2021). "Previous researchers reported that CD9 is associated with cancer cell proliferation, survival, and metastasis, which is considered a potential biomarker for cancer prognosis." (PMID 34493282, 2021). "The pooled HR was 0.47 (95% CI 0.31–0.73, p = 0.001), indicating an association between increased CD9 expression and favorable OS in cancer patients." (PMID 34493282, 2021). "In summary, an increased CD9 expression was associated with more favorable survival in cancer patients." (PMID 34493282, 2021). "Subgroup analysis was performed to explore the cause of heterogeneity according to the cancer type, CD9 detection method, publication year, race, and sample size." (PMID 34493282, 2021). "In contrast, CD26 has been shown to enhance the molecular transfer from prostasomes to epididymal spermatozoa in the stallion, and is associated with CD9 in the tetraspanin web of cancer cell lines when they became invasive." (PMID 23785420, 2013). "We chose two cancer-associated genes, CD9 and CALMODULIN 2 (CALM2), highly expressed in both cell lines, and functionally validated the role of HuR in regulating their expression." (PMID 20370918, 2010). "Given the role of CD9 expression in GC progression, the increased presence of CD9-positive vesicles in the gastric juice of cancer patients may have significant diagnostic and prognostic implications." (PMID 40565320, 2025). "Therefore, the potential of CD9 to regulate cancer progression is attributed to its association with these molecules." (PMID 38389703, 2024).
cancer (continued). "Also, CD9 is a key factor of exosomes located on their membrane and serves as an exosome marker, associated with cancer migration and invasion." (PMID 38589887, 2024). "On the contrary, an increased CD9 expression was associated with favorable survival in cancer patients, suggesting that CD9 expression could be a valuable survival factor in cancer patients." (PMID 38213729, 2024). "Furthermore, CD-9 expression was found to be increased in exosomes derived from cancer-associated fibroblasts in OCUM-12 cells and NUGC-3 cell lines, and thus is correlated with the increased migration and invasion of cancerous cells." (PMID 37834127, 2023). "Furthermore, CD9(+) EVs have been detected in the plasma of cancer patients and have the potential to be used as diagnostic and prognostic biomarkers." (PMID 37371093, 2023). "Similarly, the tetraspanin protein CD9, also highly expressed on EVs, is thought to be associated with cancer cell invasiveness by promoting EV internalization, which stimulates cellular transformation (reviewed in Ref." (PMID 37371036, 2023). "In addition, CD9 has been associated with various pathologies such as infectious diseases caused by viruses or bacteria, lung inflammation, and cancer." (PMID 35563422, 2022). "Therefore, this meta-analysis was performed to better understand the association between CD9 expression and prognosis in cancer patients." (PMID 34493282, 2021). "Furthermore, published studies report small sample sizes and individual results, making it difficult to comprehensively evaluate the association between CD9 expression and prognosis in cancer patients." (PMID 34493282, 2021). "An increased CD9 expression was associated with favorable survival in cancer patients suggesting that CD9 expression could be a valuable survival factor in cancer patients." (PMID 34493282, 2021). "CD82 or CD9 expression is generally associated with favorable prognosis in different cancers." (PMID 30769765, 2019). "Interestingly, 15-35% of cancer-associated stromal cells had nuclear CD9 signals at a frequency of 1.36 ± 0.14 (s.e.m.)per nucleus, while this event was rarely observed in distant stroma (>100 vim+ cells were evaluated per patient, n = 3)." (PMID 28129640, 2017). "The impairment of BCCs invasion into MSCs, caused either by CD9 deficiency or Ab interference, led to decrease of heterotypic cell-cell fusion – potential source of genomic instability, aneuploidy and cancer heterogeneity – hallmarks of cancer progression." (PMID 25762645, 2015). "CD9 is a 21 to 24 kDa surface molecule that belongs to the tetraspanins, a family of four-transmembrane domain proteins associated with integrin receptors, which was described as motility-related factor engaged in migration of multiple cancer cell lines." (PMID 25890097, 2015). "Loss of CD9 is correlated with cancer metastasis in many solid tumours." (PMID 21206492, 2011). "In this study, we have shown that CD9P-1 was upregulated in human cancer metastasis, suggesting that this could be one of the mechanisms underlying the loss of CD9 expression in solid tumours." (PMID 21206492, 2011). "This study has identified 32 proteins associated with CD9 including a protein complex between CD9 and epithelial cell adhesion molecule (EpCAM); (iii) a recent study has demonstrated a knock-in AP-MS approach using epitope-tagging of endogenous genes in cancer cells." (PMID 27011181, 2016). "The binding interactions between immobilized antibodies and EVs isolated from different cancer cell lines revealed a unique SPR molecular fingerprint (SPR-MFP) consisting of varying expression levels of the CD9, CD63 and CD81 EV biomarkers, as well as CXCR4." (PMID 41892066, 2026). "The elevation of Ca2+ levels in cancer cells stimulated a 5-fold increase in release of CD63+CD9+ALIX+ exosomes." (PMID 40121518, 2025). "High CD9 expression was detected in 12 cancer types, and significantly low CD9 expression was detected in only 1 cancer type." (PMID 40196737, 2025).
cancer (continued). "The identification of discrepancies in EV size and the presence of CD9 between GJ from cancer patients and healthy individuals offers potential avenues for the identification of new GC markers." (PMID 40565320, 2025). "Some clinical and experimental studies have shown that CD9 can also lead to increased proliferation, migration, and survival of cancer cells in various tissue types." (PMID 40860827, 2025). "On account of tetraspanin CD9, there is also wide preclinical research about its role in cancer, but at the moment we can only highlight two approaches that are in clinical trials." (PMID 38542421, 2024). "Antibodies targeting CD9 reduced cell surface trafficking of ADAMs and disrupted the interactions between CD9 and these ADAMs, impairing Notch activity and inhibiting the ability of cancer cells to migrate and grow." (PMID 38389703, 2024). "The CD9-HPLC-IAC technique enhances the understanding of CD9+ exosomes in cancer mechanisms and serves as a model for isolating additional exosomal subtypes." (PMID 38607736, 2024). "CD9-enriched exosomes have been found to play a role in various physiological and pathological processes, such as immune response, cancer progression, and tissue repair." (PMID 38292176, 2024). "To compensate, we validated and included common surface proteins found in most cancer types, like CD9, CD81, and human epidermal growth factor receptor 2 (HER2)." (PMID 38326078, 2024). "For that NTA‐analysis in scatter and fluorescent modes was performed with the 13 onwards S6‐FPLC fractions from the cancer patient serum incubated with the anti‐CD9‐PE antibody." (PMID 39441012, 2024). "Alternatively, a novel strategy using human-specific anti-CD9 or anti-CD63 antibodies has been adopted to deplete circulating cancer-derived EVs." (PMID 38495881, 2024). "Overall, CD9 facilitates the development of drug resistance in cancer cells and inhibits apoptosis of chemoresistance cells." (PMID 38389703, 2024). "CD9 in exosomes has been shown to play a role in promoting cell adhesion, migration, and invasion in cancer cells." (PMID 38292176, 2024). "The protein CD9, which is abundantly found on exosome surfaces, is critical in cancer research due to its connection with cancer development." (PMID 38607736, 2024). "Inhibition of CD9 expression in pancreatic ductal adenocarcinoma inhibited the uptake of annexin A6 extracellular vesicles into cancer cells and impaired annexin A6-induced cell migration and EMT processes via the p38 MAPK pathway." (PMID 38389703, 2024). "(M-Q) Phenotype switch (KIR2DL4, GZMK, CD9, CD49a, and PD-1) of NK cells was induced by cell-to-cell interactions with cancer cells." (PMID 39387546, 2024). "Nevertheless, the higher biglycan abundance in the carcinoma EVs was clearly not due to these differences as MTH53A EVs expressed similar CD9 levels as the complex carcinoma cell lines, but biglycan was hardly detectable." (PMID 39462388, 2024). "Further mechanistic experiments will elucidate the role of CD9 in particular cancer types and specific conditions." (PMID 37007105, 2023). "In the model of colon cancer blocking EV-derived CD9 by antibody prevented the morphological transformation and migratory phenotype of cancer cells that uptake EVs." (PMID 37007105, 2023). "For example, studies have shown that CD9-positive exosomes released by cancer cells can be taken up by other cancer cells, leading to the transfer of oncogenic molecules and the promotion of cancer progression." (PMID 37475778, 2023). "In such a context, it is possible that cell–cell fusion is mediated by CD9+ plasma membrane protrusions emerging from cancer cells." (PMID 37371036, 2023). "MDA-MB-231 and non-cancer-mammary epithelial MCF-10A cells derived sEVs were endowed with classic exosomal marker-tetraspanin CD9 expression." (PMID 37620316, 2023).